TYR (tyrosinase)
Diseases named in the same sentence as TYR in open-access papers (continued):
Sharing a sentence is not in itself a finding about the gene and the disease.
melanoma (continued). "In current practice, melanomas are diagnosed with the most sensitive markers SOX-10 and S100, and at least one of the more specific markers such as MART-1 or Melan A, HMB45, and tyrosinase." (PMID 39258061, 2024). "Calycosin significantly inhibited the expression of melanin-related genes (including MITF, TYR, and TRP-1) in B2F16 melanoma cells to regulate MSH-induced melanogenesis." (PMID 38586368, 2024). "Drosophila-derived aAPCs were transduced with HLA-A*0201 and pulsed with tyrosinase peptides to expand tyrosinase-specific CD8+ T cells, which were infused into melanoma patients subsequently." (PMID 39215816, 2024). "Markers like HMB-45, HMB-50, tyrosinase, melan-A, and MITF also show differences in expression between these two types of melanomas." (PMID 38392052, 2024). "Additionally, melanoma cell lines were used to assess the effects of the extracts and their potential compounds on cell viability, melanin production within the cells, and intracellular tyrosinase activity, indirectly determined by measuring the amount of L-dopachrome formation." (PMID 39684912, 2024). "Second, our data suggests a correlation of NY-ESO-1, tyrosinase, and MAGE-A3 expression in melanomas with patient age." (PMID 38890171, 2024). "Specifically, overexpression or exogenous treatment has been shown to decrease the expression of MITF, TYR, TYP1, and TYP2 and reduce the melanin production in melanoma cells or melanocytes." (PMID 39000342, 2024). "As kuraridin exhibited the highest tyrosinase inhibition at the cell-free level, its inhibitory effect on tyrosinase activity and melanin production was further investigated in B16F10 melanoma cells." (PMID 39457011, 2024). "Taken together, these data suggest that 50 EtOH and 95 EtOH can alleviate melanogenesis in human melanoma cells with inhibitory effects against MITF, TYR, TRP-1, and MC1R mRNA expression." (PMID 39335872, 2024). "Our study suggests that 10E-PDA can inhibit melanogenesis in B16F10 melanoma cells by blocking MITF nuclear translocation and reducing downstream melanogenesis factors such as tyrosinase and TRP-1 at both the mRNA and protein levels." (PMID 39765875, 2024). "Treatment with AM-EO reduces melanogenesis through the regulation of tyrosinase activity and the Jun N-terminal kinase -ERK pathway in α-MSH-stimulated B16 melanoma cells." (PMID 38791435, 2024). "The treatment with CF-EO inhibits melanogenesis by inhibiting tyrosinase activity and by reducing TRP-1 and TRP-2, co-stimulated with α-MSH and forskolin (FSK), in B16F10 melanoma." (PMID 38791435, 2024). "Our study demonstrated that treatment with B. alba extracts resulted in the downregulation of melanin production, along with a reduction in cellular tyrosinase activity, in IBMX-induced melanoma models." (PMID 39335872, 2024). "The present study confirmed that kuraridin exhibited the most remarkable inhibitory effect on tyrosinase activity in cell-free and α-MSH-induced melanoma cells." (PMID 39457011, 2024). "It is composed of four TAAs that are present on both MHC class I and class II molecules—NY-ESO-1, MAGE-A3, tyrosinase, and TPTE—which express at restricted levels in normal tissues but have a high prevalence and immunogenicity in melanoma." (PMID 38732242, 2024). "Prior research has underscored the pivotal role of MITF in transcriptionally regulating melanogenic enzymes, including tyrosinase, TRP-1, and TRP-2, thereby modulating melanogenesis in melanoma cells." (PMID 38794376, 2024). "RES has also presented the ability to modulate tyrosinase activity, reducing the expression of melanogenesis-related proteins, including tyrosinase, TRP, and MITF in melanoma cells." (PMID 39204367, 2024). "The melanin production is attenuated by treatment with VZ-EO through the inhibition of tyrosinase activity and anti-oxidant activity via the regulation of GSH level and anti-oxidant enzymes, GPx and SOD, in α-MSH-stimulated B16 melanoma cells." (PMID 38791435, 2024).
melanoma (continued). "The anti-melanogenic effects of B. alba were mediated through the inhibition of the regulator gene MITF and the downregulation of pigmentary genes, such as TYR, TRP-1, and DCT, in the human melanoma cells exposed to cAMP stimulator IBMX." (PMID 39335872, 2024). "As expected, TNF decreased the gene expression of MITF and its target genes MLANA, DCT and TYR, and, conversely, increased the expression of the stemness factor NGFR in 451Lu melanoma cells." (PMID 39136013, 2024). "HCP inhibits the activity of tyrosinase and decreases the amount of proteins related with melanogenesis by antagonizing the effect α-MSH- and ET-1-induced on MNT-1 human melanoma cells and promoting the transfer to keratinocytes." (PMID 37108635, 2023). "Firstly, we assessed the impact of subjected compounds on tyrosinase activity using amelanotic (A375, Sk-Mel-28) and highly pigmented (melanotic) (MNT-1) melanoma cells." (PMID 37834395, 2023). "The polyphenol-enriched Rosa rugosa extract exerts similar effect as observed in the current study by reducing the mRNA and protein expression levels of MITF, tyrosinase, TRP-1, and TRP-2 in murine melanoma cells." (PMID 37511600, 2023). "In this study, the ethanolic extracts from twelve seaweeds were assessed for tyrosinase-inhibiting activity using mushroom tyrosinase and melanin synthesis in B16F10 melanoma cells." (PMID 37109464, 2023). "The results showed that both acenocoumarol and warfarin did not cause any cytotoxicity and resulted in a significant reduction in intracellular tyrosinase activity and melanin content in B16F10 melanoma cells." (PMID 37111361, 2023). "The melanoma markers MLANA (MART-1), TYR, HMB45 (PMEL), SOX10, S100, and the proliferation marker MIB-1, which recognizes the Ki67 antigen, are used to diagnose primary and metastatic melanoma." (PMID 37762707, 2023). "AmIV extracts were shown to increase the activity of mushroom tyrosinase and tyrosinase present in B16F10 murine melanoma cells." (PMID 37375348, 2023). "Cell-based assays, performed on α-MSH-stimulated B16F10 melanoma cells, showed that MHY1498 (53a) was able to decrease melanin synthesis by reducing TYR activity." (PMID 37240442, 2023). "Tyrosinase inhibition, kinetic enzyme assays, and molecular docking studies were conducted using mushroom tyrosinase in order to examine the antioxidant mechanism and antimelanin activity of EG in B16F10 melanoma cells." (PMID 36829827, 2023). "exhibited anti-melanogenic activity by suppressing tyrosinase activity, TRP-1 expression, and TRP-2 expression in B16-F10 mouse melanoma cells." (PMID 37511600, 2023). "The results revealed that the CSTB, GBF1, TYR, RAC1, SLC2A1 and NOTCH3-coding proteins were significantly enriched in melanoma samples, while CEBPB-coding protein had low expression in melanoma samples." (PMID 37217516, 2023). "The mechanism of vitiligo seen in patients treated with CIs is thought to be a cross-reaction between the shared antigens in melanoma and normal melanocytes, such as MART1, GP100, or tyrosinase." (PMID 38259857, 2023). "Meanwhile, the cactus extracts were also applied oneself on preventing tyrosinase mRNA expression and melanin synthesis in IBMX-treated B16-F10 melanoma cells." (PMID 36627306, 2023). "Metastatic melanoma is also S100 positive, but will be positive for more specific markers such as HMB45, melan A, tyrosinase and microphthalmia transcription factor." (PMID 38163055, 2023). "Five of nine identified ER stress-related genes, CEBPB, TYR, SLC2A1, NOTCH3 and RAC1, have been reported to engage in melanoma malignant behavior regulation." (PMID 37217516, 2023). "The tyrosinase promoter-driven NPTyr-C9AP can specifically co-express CXCL9 and αPD-L1 in melanoma cells, thereby forming a CXCL9 gradient for T-cell recruitment and high intratumoral αPD-L1 concentration for enhancing T-cell activation." (PMID 37031188, 2023).
melanoma (continued). "Cell-free mushroom tyrosinase activity of the hot water extract of A. cochinchinensis and five steroidal saponins, including ACC, was determined in both murine B16F10 and human melanoma MNT1 cells." (PMID 37684311, 2023). "The protein expressions of TYR, TRP-1 and DCT in MNT-1 melanoma cells were detected by Western-blot assays." (PMID 37108635, 2023). "Accompanying the down regulation of pigmentation specific proteins such as tyrosinase and TYRP1, these biomarkers are highly specific for a type of highly invasive melanoma." (PMID 36776379, 2022). "While C7R has a lower effect on inhibition of purified mushroom tyrosinase compared to kojic acid, it inactivates tyrosinase in B16F10 melanoma cells as much as kojic acid." (PMID 35919819, 2022). "The downregulation of TYR and TRP1 in siADCK2-treated melanoma cells confirmed the switch to a more migrative and invasive behavior." (PMID 35205819, 2022). "First, we identified tumor cells by inferred large-scale CNVs from single-cell expression profiles and newly identified PMEL, S100B, SERPINE2, TYR, and PRAME as marker genes for melanoma malignant cells." (PMID 35646893, 2022). "This transcription factor that promotes the expression of the most melanogenic proteins including TYR, TYRP1, DCT and PMEL, was found to be also critical for melanoma invasion and proliferation upon down-regulation in melanoma cells." (PMID 36776379, 2022). "We also examined the transcription of melanin synthesis genes TYR, TYRP1, PMEL, MLANA and DCT by RNAseq analysis in M14 human melanoma cells in which we have disrupted TXNRD1 using Crispr/Cas9 (M14TXNRD1+/− cells)." (PMID 36291795, 2022). "Collagen stiffness induced the expression of melanoma differentiation genes TRPM1, PMEL, TYR and MLANA, as well as well as the proliferation and survival genes CDK2 and BCL2A1." (PMID 36135194, 2022). "Moreover, the cell-based evaluation using B16F1 and B16F10 melanoma cells demonstrated that dihydrostilbene analogues I and II exhibited a stronger anti-melanogenic effect than kojic acid through the inhibition of cellular tyrosinase activity and melanin formation." (PMID 36009312, 2022). "Representative synthetic compounds with inhibitory and activating properties were further evaluated in melanoma cell lines B16F1 and B16F10 for their ability to moderate tyrosinase activity and affect melanin production." (PMID 36009312, 2022). "The hot water extract of Pleurochrysis carterae inhibited melanin synthesis by downregulating the tyrosinase and MITF levels in B16F1 melanoma cells." (PMID 35883808, 2022). "The melanoma cells were treated with 20, 40, and 60 μg/mL of PP60, and tyrosinase expression was induced by using L-DOPA." (PMID 36091602, 2022). "After confirming that the tumors generated on the CAM model are of melanoma origin by pan melanoma marker staining (HMB1, Tyrosinase, and S100), we treated the resulting tumors with different concentrations of NT157." (PMID 36551732, 2022). "A plethora of molecules have been evaluated for their potential clinical values as melanoma biomarkers, such as lactate dehydrogenase (LDH), tyrosinase, and PD-L1." (PMID 36012593, 2022). "Immunohistochemical analysis of the original tumor sample and the PDCs confirmed the expression of melanoma markers (HMB-45, MART-1 (Melan A), and Tyrosinase) in the PDCs." (PMID 34837846, 2022). "Melanoma is a highly malignant tumor derived from melanocytes, which differentiate via melanogenesis regulated by melanocortin 1 receptor (MC1R), tyrosinase (TYR), TYR-related protein-1 (TYRP1), and dopachrome tautomerase (DCT)." (PMID 35619714, 2022). "Gene signatures from group 2 corresponded to a proliferative and differentiated phenotype of melanoma (DCT, MLANA, TYR)." (PMID 35053440, 2022).
melanoma (continued). "For this stage, there are several markers for melanoma-initiation, such as MAGE proteins, GalNAc-T, NG2, CSPG4, ABCB5, MAGEA3, PAX3, TGFB2, TYR2, Human Melanoma Black-45 (HMB-45), Melan-A, tyrosinase, and S100." (PMID 35565234, 2022). "The addition of DLGFLARGF significantly inhibited the tyrosinase activity and melanin production of B16F10 melanoma cells." (PMID 35369091, 2022). "The tyrosinase inhibitory effects of UA and UB and cytotoxicity were evaluated in B16F10 melanoma cells." (PMID 36437391, 2022). "This study demonstrated the anti-melanogenic activity of calycosin, a common dietary isoflavonoid, by decreasing expressions of MITF and its target genes tyrosinase and TRP-2 in B16F10 melanoma cells." (PMID 35163281, 2022). "In contrast, EGCG showed the ability to inhibit the activity of the tyrosinase enzyme and to also decrease the melanin content in the B16F10 cell line (mouse melanoma cell line)." (PMID 35877341, 2022). "Ferulic acid was proposed as the most active murine tyrosinase inhibitor, responsible also for the reduced melanin release from B16F10 murine melanoma cells." (PMID 33670416, 2021). "According to this evidence, EVs derived from Dendropanax morbifera, both from leaves and stems, inhibited melanogenesis by reducing the expression of TYR, TRP-1, and TRP-2 in B16BL6 cells (mouse melanoma)." (PMID 34065193, 2021). "Compound 2a at concentrations ≤ 20 μM was found to inhibit cellular tyrosinase activity and melanogenesis effectively and dose-dependently in α-MSH plus IBMX stimulated murine B16F10 melanoma cells." (PMID 34070680, 2021). "Meanwhile, we also turned to TCGA Skin Cutaneous Melanoma (SKCM) database to analyze the correlation between CD27-AS1 level and the expressions of MITF, TYR and PMEL in melanoma." (PMID 35096622, 2021). "In melanoma cells, β-catenin activates proteins involved in melanogenesis and pigmentation such Melan-A, dopachrome tautomerase (DCT) and tyrosinase, all through MITF." (PMID 34356645, 2021). "Moreover, using the co-culture system, we showed that inhibition of the tyrosinase activity in melanoma cells modulates cytokine expression in co-cultured mononuclear cells, indicating that depigmentation of melanoma cells may activate immune cells and thereby influence a host anticancer response." (PMID 34072104, 2021). "CREB phosphorylation by ICG-001 was markedly inhibited in melanoma cells pretreated with the PKA inhibitor H89, resulting in the inhibition of pigmentation and tyrosinase activity." (PMID 33918792, 2021). "Our observations indicated that CJS-EO inhibited α-MSH-induced melanogenesis through tyrosinase inactivation and the simultaneous suppression of the expression of proteins involved in melanin biosynthesis in B16F10 melanoma cells." (PMID 34824592, 2021). "First, we compared the effects of twenty different amidated amino acids on tyrosinase (TYR)-mediated dopachrome formation in vitro and melanin content in dark-pigmented human melanoma MNT-1 cells." (PMID 34439449, 2021). "In cultured B16F10 melanoma cells, TNF-α reduced the expression of TYR and TRP1 and TYR activity in a dose-dependent manner." (PMID 34603597, 2021). "According to our results, among the flavonoid glycosides tested in this study, only JUB, EPA, and FRS effectively inhibited α-MSH-induced melanogenesis in both B16F10 melanoma cells and zebrafish larvae by inhibiting the cAMP-CREB-MITF-tyrosinase axis." (PMID 34299326, 2021). "A large number of other melanocytic markers have been subsequently investigated including HMB45, Melan A, tyrosinase, MITF, and SOX10, and are increasingly used in the diagnosis of melanoma." (PMID 34449584, 2021). "Cytotoxicity and Tyrosinase inhibitory effects of UA and UB were evaluated in B16F10 melanoma cells." (PMID 34201391, 2021). "Tyrosinase (TYR) is a critical enzyme in melanin metabolism, with abnormal expression closely related to vitiligo, melanoma, and Parkinson’s disease." (PMID 34107850, 2021).
melanoma (continued). "In a follow-up study, we intend to investigate a potential correlation between TYR RNA expression levels by OMMs and their responsiveness to the ONCEPT® canine melanoma vaccine." (PMID 34422947, 2021). "In daily practice, the IHC-panel usually includes S100 protein and at least one of the three members of the conventional pan-melanoma cocktail: Human melanoma black 45 (HMB45), MART1/melan-A, and tyrosinase." (PMID 33801642, 2021). "The α-piceid isomers also showed better inhibitory activity against tyrosinase and melanin synthesis in B16F10 melanoma cells than β-piceid." (PMID 34584041, 2021). "Compound 2a inhibited cellular tyrosinase activity and melanogenesis in α-MSH plus IBMX-stimulated B16F10 melanoma cells more strongly than KA." (PMID 34070680, 2021). "Most of the MM cases (85.71%) were positive for both conventional- and conventional-adapted pan-melanoma cocktail (triple positivity for HMB-45, tyrosinase, and SOX10) with a significantly higher rate compared with naevi (p < 0.0001)." (PMID 33801642, 2021). "The patient underwent surgical resection of the tumor, and was pathologically diagnosed as neonatal congenital malignant melanoma; immunohistochemistry (IHC): S-100 (+), HMB45 (+), Melan A (+), and Tyrosinase (+)." (PMID 33706747, 2021). "It is also known that daidzein and EQ 1 decrease the expression of tyrosinase, tyrosinase-related protein-1 (TRP-1), and tyrosinase-related protein-2 (TRP-2), thereby blocking melanin production in α-MSH-stimulated B16 melanoma cells." (PMID 34502054, 2021). "In this study, we demonstrated that morin induced melanin synthesis and tyrosinase activity by accelerating ERK and p38 signaling pathways in B16F10 mouse melanoma cells." (PMID 33917985, 2021). "Stimulation of α-MSH in B16-F10 melanoma cells increased the expression of MITF and the melanogenesis-related tyrosinase gene family (TRP-1, TRP-2, and tyrosinase) through the activation of CREB and ERK." (PMID 33804361, 2021). "We next applied cell-based assays on B16-F10 melanoma cells to determine the inhibitory effect of OLM and its different soluble fractions on cellular melanin content and tyrosinase activity." (PMID 33917957, 2021). "Since then, numerous clinical studies in melanoma patients have been performed using moDCs loaded with MAGE-, MART-, gp100-, or tyrosinase-derived peptides." (PMID 34066067, 2021). "This compound potently suppressed melanin synthesis by ten times more than arbutin via the regulation of MITF, tyrosinase expression and CREB signaling pathways in murine melanoma B16-F10 cells." (PMID 34946631, 2021). "Melanomas are usually immunoreactive for Melanoma antigen recognized by T-cells-1 (MART-1) or melan A, S-100 protein, melanoma-specific antigen (HMB-45), tyrosinase, and Microphthalmia transcription factor (MITF)." (PMID 34209084, 2021). "Cha and Kim demonstrated that cordycepin can suppress cellular tyrosinase activity and melanin production in cultured B16F0 melanoma cells." (PMID 34829260, 2021). "In the group of naevi, the positivity rate for the conventional pan-melanoma cocktail was 43.18% (n = 19), respectively, 54.54% for HMB-45 (n = 24), 59.09% for tyrosinase (n = 26), and 84.09% for melan-A (n = 37), when examined individually." (PMID 33801642, 2021). "In B16-F10 melanoma cells, OLM and its fractions significantly decreased melanin production and tyrosinase activity." (PMID 33917957, 2021). "Stichopus japonicus extracts were evaluated by measuring the inhibition of mushroom Tyrosinase and melanogenesis in B16F10 melanoma cells." (PMID 34201391, 2021). "As demonstrated in UMM066, CYSLTR2 expression was found in melanoma cells that also presented with high expression of pigmentation genes (MITF and TYR) and marker genes of MAPK (Mitogen-Activated Protein Kinase) pathway activation (MPAS)." (PMID 33588787, 2021).